CTLA4 (cytotoxic T-lymphocyte associated protein 4)
Diseases named in the same sentence as CTLA4 in open-access papers (continued):
Sharing a sentence is not in itself a finding about the gene and the disease.
tumor (continued). "iTSCM cells also exhibit decreased expression of the T-cell inhibitory receptors programmed cell death-1 (PD-1) and cytotoxic-T-lymphocyte-associated protein 4 (CTLA-4), allowing for enhanced survival and activation in the tumor microenvironment." (PMID 30967879, 2018). "Targeting immune checkpoint receptors (e.g., PD-1, CTLA-4) has emerged as a promising new approach to enhance anti-tumor immune responses." (PMID 30400822, 2018). "Other studies have found that blockade of PD-1 increased the expression of other immune checkpoint molecules on tumor-infiltrated immune cells, including Tim-3, CTLA-4, and LAG-3." (PMID 30309387, 2018). "The emergence of immune checkpoint inhibitors, such as anti-PDL-1, anti-PD-1, and anti-CTLA-4, which have good efficacy in many tumor models, raises the question of the pertinence and safety of their combination with radiation." (PMID 30487462, 2018). "Blockade of the CTLA-4 pathways is now being widely used in the clinic to reverse the dysfunctional phenotype of tumor-specific T cells and enhance their ability to kill tumor cells." (PMID 30127783, 2018). "Accordingly, antibody blockade of CD96 promotes NK cell production of IFN-γ and leads to improved tumor control of lung metastases in three different mouse models, both alone or, more effectively, in combination with anti-CTLA-4, anti-PD-1, or doxorubicin." (PMID 30250471, 2018). "Anti-CTLA-4 antibodies have also been shown to broaden the immune response as well as deplete tumour resident regulatory T-cells (Tregs)." (PMID 29570634, 2018). "Combined therapy with CTLA-4 and PD-1 blockade was associated with a greater enhancement in tumor induced lymphocyte (TIL) activity and proliferation similar to CTLA-4 or PD-1 blockade alone." (PMID 29769148, 2018). "In a separate study using KPC mice, depletion of FAP+ stromal cells was synergistic with anti‐CTLA‐4 or anti‐PD‐L1 therapy, further demonstrating the role of stroma in suppressing anti‐tumor immunity." (PMID 30003190, 2018). "Similar to anti-CTLA-4 immunotherapy, anti-PD-1/PD-L1 monoclonal antibodies also play a positive role in tumor therapy and achieve greater progress when combined with radiotherapy." (PMID 29958545, 2018). "Blocking of this inhibitory pathway with anti-CTLA-4 antibodies, results in re-invigorated T cells with greater proliferative function, and durable anti-tumor potency." (PMID 29843813, 2018). "As demonstrated by our data, PTX apparently inhibited PD-1 and CTLA-4 in spleen but upregulated PD-1 in the tumor, implying a possible induction of anergy on the tumor immune surveillance." (PMID 30108589, 2018). "CTLA-4 is also expressed by activated populations of regulatory T (Treg) cells, which can impair productive anti-tumor immunity through a variety of suppressive mechanisms." (PMID 29617360, 2018). "PD-1 and PD-L1, but also CTLA-4, are differently expressed in tumor cells and in diverse subsets of immune cells." (PMID 30577587, 2018). "Ipilimumab is a fully humanized IgG1 monoclonal antibody that inhibits the CD28/CTLA-4 interaction, thereby promoting T cell activation and resulting in anti-tumor immunity." (PMID 30170622, 2018). "Previously, zirconium-89 labeled anti-CD3 indicated a strong correlation between anti-CTLA-4–treated mice and tumor volume." (PMID 29513764, 2018). "Our results show that tumor environment alters the promoter methylation profile of PD-1, CTLA-4, and TIM-3 to extremely hypomethylated state." (PMID 29983831, 2018). "In our study in ALNs, higher levels of CTLA-4+ T cells were demonstrated in ALN metastases than in the corresponding primary tumours." (PMID 29390966, 2018). "TN are a key source of secondary anti-tumor immunity mediated by antigen spread in response to checkpoint blockade and are highly sensitive to anergy imposed by expression of CTLA-4." (PMID 29891009, 2018).
tumor (continued). "CTLA-4 inhibition induces rapid proliferation and expansion of T cells, while PD-L1 blockade overcomes adaptive immune resistance on the tumor itself by enhancing the efficacy of effector T cells." (PMID 29377881, 2018). "A potential explanation is chronic TCR stimulation within the tumor resulting in increased expression of activation/exhaustion markers, some of which participate in the downregulation of immune function (e.g., PD-1, CTLA-4 and TIM-3)." (PMID 30006565, 2018). "In contrast, mice exposed to dexamethasone prior to tumor implantation and antigen exposure were unresponsive to CTLA-4 blockade." (PMID 29891009, 2018). "We found that in PD-1 and CTLA-4 promoters, both repressive histones bind weakly in tumor tissues compared with normal tissues." (PMID 29983831, 2018). "One recent study evaluated these changes in tumor-free and tumor-bearing mice that received peripheral radiotherapy or immunotherapy (anti-CTLA-4 antibody) or both." (PMID 29930550, 2018). "We also demonstrated that anti-CTLA4 treatment can promote the abscopal effect to distant tumor sites after the primary tumor received local radiation." (PMID 29699510, 2018). "Recent research indicated that HDAC inhibitors can enhance the efficacy of an antibody targeting CTLA-4 by modulating the relationship between immune and cancer cells, hence upregulating the recognition and elimination of tumor cells." (PMID 30558227, 2018). "In mice with subcutaneous KPC tumors, treatment with anti‐PD‐1 or anti‐CTLA‐4 enhanced the anti‐tumor effects of chemotherapy and agonist CD40 treatment." (PMID 30003190, 2018). "Further tumor regression was achieved by the addition of anti-PD-L1 and anti-CTLA-4 treatment in both MC38 and CT26 tumors." (PMID 30766539, 2018). "For ID8-VEGF, tumor regression was observed in 25% of test animals after PD-1 blockade, 25% with CTLA-4 blockade, and 37.5% with PD-L1 blockade, as compared to 50% with combined CTLA-4 plus PD-1 or PD-L1 blockade." (PMID 29769148, 2018). "The metaplastic CTLA-4+/Vimentin+ tumor cells likely derived from an epithelial mesenchymal transition process and trans-differentiation of spindle cells that have up-regulated mesenchymal markers." (PMID 29682176, 2018). "On the contrary, IDO-knockout mice treated with anti-CTLA-4 or anti-PD-1/PD-L1 demonstrate significant tumor growth regression and prolonged survival, and combination treatment of IDO inhibitors and CTLA-4 blockade has achieved remarkable tumor rejection." (PMID 30294272, 2018). "As already mentioned, recent cancer immunotherapies have targeted the molecules in the tumor microenvironment of immune check point inhibitors including CTLA4, PD-1 or ICOS." (PMID 29988281, 2018). "Treatment with anti-CD40L at tumor implantation blocked the efficacy of radiation therapy combined with anti-CTLA4 in the CT26 tumor model (p < 0.01) and the Panc02-SIY tumor model (p < 0.05)." (PMID 29725089, 2018). "We have previously characterized the TCRb repertoire of expanded and activated CD8+ T cells recognizing the AH1 epitope from gp70 antigen (a tumor antigen expressed by 4T1 cells) in tumors of mice treated with RT+anti-CTLA-4." (PMID 30400822, 2018). "Checkpoint inhibitors, such as anti-PD-1 and anti-CTLA-4 antibodies, have been shown to have good therapeutic effects in many tumours, leading to significant durable survival, thus a number of these are currently approved for clinical use." (PMID 29570634, 2018). "In tumor tissues, many Tregs develop into effector Tregs which express CTLA-4, PD-1 or CCR6 at higher levels, and engage in the disruption of host immune systems including those in OSCC patients." (PMID 29988281, 2018). "HDAC is have been shown to sensitize cancer cells to immune checkpoint therapy by upregulating the immune checkpoints CTLA-4, PD-1, PD-L1, and PD-L2 on tumor cells and TILs." (PMID 29843754, 2018).
tumor (continued). "In the clinical setting, PD-1 blockade demonstrated evidence of anti-tumor immunity in multiple cancers, with less immunotoxicity than with systemic CTLA4 blockade." (PMID 29692957, 2018). "Ipilimumab, an antibody targeting CTLA-4, appears to restore tumor immunity at the priming phase and prolongs overall survival in some patients, whereas anti-PD-1/PD-L1 antibodies restore immune function in the tumor microenvironment." (PMID 29615812, 2018). "In contrast to VEGF and EGF, PD1/PD-L1, as well as CTLA-4 are immune checkpoints that negatively regulate T-cell immune functions, thus indirectly promoting tumor progression via tumor immune escape." (PMID 30577587, 2018). "Co-administration of imatinib with anti-CTLA-4, the T cell modulator showed greater tumour regression compared with single treatment." (PMID 29455663, 2018). "Myofibroblast depletion combined with anti-CTLA-4 antibodies significantly reduced the tumor burden in mice." (PMID 30428588, 2018). "Extracellular adenosine, a by-product of altered tumor metabolism, induces expression of both CTLA-4 and PD-1 on T cells." (PMID 29482595, 2018). "The first study, carried out by Alison and colleagues demonstrated that CTLA-4 blockade enhances the anti-tumor immune response." (PMID 28866656, 2018). "In a group of 11 women treated with the GVAX vaccine (autologous tumor cells engineered to secrete GM-CSF) followed by ipilimumab (anti-CTLA-4), one patient had a dramatic fall in her CA-125 levels and 3 other patients achieved stabilization of their disease." (PMID 30421009, 2018). "Average tumor growth curves also showed significant differences for treatment when the combination of vaccine with anti-PD-L1 and anti-CTLA-4 was compared to control (p = 0.0007, 2-way repeated measures ANOVA)." (PMID 29377881, 2018). "Using murine tumor models we assessed the effect of anti-CTLA4 administration on intratumoral and peripheral immune cells including NK cells." (PMID 30400822, 2018). "How modulation of the PD-1 pathway together with CTLA-4 blockade alters tumor-specific versus other memory T cell responses remains to be examined." (PMID 29617360, 2018). "In a follow-up study by the same group, abscopal effect of combined radiation and CTLA-4 blockade was demonstrated using bilateral tumor models in which the unirradiated tumors displayed significant growth delay after irradiation of the primary tumors." (PMID 30558196, 2018). "Pancreatic cancer cells can induce the expression of proteins (e.g., CTLA4, or PD-L1) and the secretion of cytokines (e.g., GM-CSF) that prevent effector T cells from infiltrating and destroying the tumor 40,41." (PMID 30365605, 2018). "More seriously, in a study on a mixed cohort of cancer patients, CTLA-4 or PD-1 blockade was found to induce a 2-fold increase in tumor development and 50% increase in tumor burden." (PMID 30191140, 2018). "PD-1 and CTLA-4 are extensively being studied and are considered as potential targets for activating the tumor infiltrating T cells that remain inactive in the immunosuppressive tumor microenvironment." (PMID 30356330, 2018). "The comparative in vivo effect of a-CTLA4-TGFβRII and a-CTLA-4 on the differentiation of tumor-infiltrating T cells into central memory T cells (CD45ROhighCD62Lhigh) was also evaluated in tumors collected from PDX-bearing immune-reconstituted mice." (PMID 29467463, 2018). "They show that tumor growth was significantly inhibited and that the expression of PD-1 and CTLA-4 in the tumor tissue significantly decreased after the introduction of siPD-1 and siCTLA-4." (PMID 30564277, 2018). "A decrease in tumor growth and in Treg and CTLA-4 levels was observed following TIM-3 blockade, while M2 macrophage markers were not altered." (PMID 29976244, 2018). "Systemic administration of anti-CTLA-4 or anti-PD-L1 together with intratumoral MV delayed tumor progression and prolonged survival, which was also observed with local, MV-mediated ICI expression." (PMID 29857493, 2018).
tumor (continued). "Here, we review data implicating CTLA-4 and PD-1 in the motility of T-cells with a specific reference to the potential exploitation of these pathways for more effective tumor infiltration and eradication." (PMID 30542345, 2018). "Among patients with non-small-cell lung cancer and a high tumor mutational burden, significantly longer PFS occurred with combination therapy of PD-1 antibody nivolumab and CTLA-4 antibody ipilimumab than with chemotherapy." (PMID 30305604, 2018). "Regarding to CTLA-4, tumor xenograft made an evident upregulation on mRNA and protein level in spleen, while both treatments of PTX and ESG decreased them significantly." (PMID 30108589, 2018). "Any of these mutations would prevent signaling in response to IFN-γ and give an advantage to the tumor cells in escaping from T cell attack, thereby resulting in primary resistance to anti-CTLA-4 therapy." (PMID 29482595, 2018). "The therapeutic efficacy of PD-1 and/or CTLA-4 blockade is thought to rely largely on the rescue of tumor-specific T cells from exhaustion and restoration of their effector functions." (PMID 30250471, 2018). "Now, CARs that can secrete PD1 and/or CTLA4 antibodies have been designed to improve immunosuppression and enhance anti-tumor effect in clinical trials and it has been demonstrated that tumor volume can be decreased by PD1 specific CARs." (PMID 29568411, 2018). "In both of these cases, the goal is to be able to find a pharmacological method to achieve CTLA-4-based activity directed towards the tumor and sparing normal tissues." (PMID 30376867, 2018). "Here, our work shows that the combination therapy targeting the sialoglycan/Siglec pathway and PD-1 or CTLA-4 inhibition induces tumor control in different preclinical mouse models and increases T cell activation in primary patient tumor samples." (PMID 30400822, 2018). "Combining CAR T cells with other therapies like CTLA-4 and PD-1 inhibitor offers the potential to improve anti-tumor effects." (PMID 29980239, 2018). "Check-point blockade of cytotoxic T lymphocyte antigen 4 (CTLA-4, CD152) is a major focus in tumor immunotherapy." (PMID 30542345, 2018). "We find that a-CTLA4-TGFβRIIecd is significantly more effective in reducing and counteracting tumor-infiltrating Tregs, activating antitumor immunity, and inhibiting tumor progression compared with the CTLA-4 antibody, Ipilimumab." (PMID 29467463, 2018). "Targeting the immune checkpoint receptors cytotoxic T lymphocyte antigen 4 (CTLA-4), programmed cell death protein 1 (PD-1), or programmed cell death 1 ligand 1 (PD-L1) represents a very attractive treatment modality for tumor patients." (PMID 29494517, 2018). "Immunomodulatory antibodies, such as CTLA-4-, PD-1-, and PD-L1-specific mAbs, target the patient immune system to overcome immunosuppression induced by tumor cells and generate an antitumor immune response." (PMID 30321186, 2018). "The tumor-bearing mice were randomly divided into four groups: control, single PD-1 siRNA, single CTLA-4 siRNA, and double PD-1 + CTLA-4 siRNAs." (PMID 30564277, 2018). "The introduction of the scoring systems for CTLA-4 and PD-L1 expression are intended to facilitate a more systematic correlation between the tumor expressivity and potential stratification of the responses to the cancer treatments." (PMID 29672601, 2018). "Overall, downregulation of PD-1 or CTLA-4 had a significant inhibitory effect on the growth of the tumor." (PMID 30564277, 2018). "A systematic literature review and meta-analysis was performed on dendritic cell (DC), tumor associated macrophages (TAM), mast cells (MC), natural killer (NK) cells, T and B cells and tumor CTLA-4 and PD-L1 studies." (PMID 29872507, 2018). "CTLA-4 and PD-1 are the representative examples, and their blockade by therapeutic antibodies leads to enhanced anti-tumor immunity with durable clinical responses, but only in a minority of patients." (PMID 30250471, 2018).
tumor (continued). "By reinvigorating the immune system, immunomodulatory antibodies (anti-CTLA-4, anti PD-1) can promote anti-tumor immunity but also the development of irAEs." (PMID 29606147, 2018). "CD8+ tumor-infiltrating T cells (TILs) were isolated from the tumors of mice treated with α-CTLA-4 plus vaccine." (PMID 29377881, 2018). "Immunosuppressive tumor mechanisms include checkpoint inhibitor mAb's targeting inhibitory T-cell checkpoints of PD-1 and CTLA-4, and other targeted antibodies (e.g., against CD25) that deplete inhibitory regulatory Treg cells." (PMID 30191140, 2018). "Blocking the PD-1/PD-L1 signaling pathway inhibited the growth of a variety of malignant tumors, and downregulation of CTLA-4 also showed great potential for tumor suppression." (PMID 30564277, 2018). "Although effect of ESG on the protein expressions was not exactly consistent with that on mRNA level, it was also found that protein expression of PD-1 was significantly suppressed in tumor, whereas that of CTLA-4 was only downregulated in spleen." (PMID 30108589, 2018). "They promote tumor growth by diverse mechanisms, including expression of immune checkpoints (CTLA-4, PD-1 and others) as well as production of IL10 and transforming growth factor-beta (TGF-β)." (PMID 29970158, 2018). "These immune checkpoint molecules including PD-1 and CTLA-4 are highly expressed on tumor infiltrating and peripheral lymphocytes, and their ligands are up-regulated in many human cancers." (PMID 30040869, 2018). "Tregs in BM and tumor-infiltrating T cells isolated from tumor-bearing mice treated with either a-CTLA4-TGFβRII or a-CTLA-4 and their untreated counterparts were measured by immunophenotype analysis." (PMID 29467463, 2018). "In contrast to pre-treatment biopsies, tumor biopsies in early treatment phase in metastatic melanoma patients treated with sequential CTLA-4 and PD-1 blockade showed high expression of PD-1 and PD-L1 in responders." (PMID 29970158, 2018). "The mechanism of action for the PD-1/PD-L1 pathway is different from CTLA-4 signaling; when PD-L1 protein expresses on tumor cells or immune cells in the TME, this results in inhibition of T-cell function." (PMID 29358573, 2018). "Fc-gamma receptors (FcγRs) expressed by M2 TAMs facilitate anti-tumor response to CTLA-4 inhibition through Treg depletion." (PMID 29970158, 2018). "Using murine tumor models, we found that anti-CTLA4-induced Treg depletion coincided with activation and degranulation of intratumoral NK cells." (PMID 30400822, 2018). "By limiting CD28-mediated signaling during antigen presentation, CTLA-4 increases the activation threshold of T cells, reducing immune responses to weak antigens such as self- and tumor antigens." (PMID 29644214, 2018). "Synergizing their corresponding blockades would abrogate Treg cell-mediated immunosuppressive effects and enhance CD8+ and NK cell function within tumor tissues, demonstrating improved safety profiles over CTLA-4 and PD-1 inhibitors." (PMID 30191140, 2018). "Given the aggressive nature of the MB49 model and a relatively modest effect of single-agent CTLA-4 blockade seen in humans, a lower tumor challenge was used compared to the PD-1 combination experiments." (PMID 29983890, 2018). "Pairing CTLA-4 blockade along with PD-1/PD-L1 blockade has been effective in other tumor types to enhance the immune response and is being further explored in UCs in multiple ongoing clinical trials." (PMID 29977169, 2018). "Despite marked T-cell expansion and tumor infiltration following whole cell vaccination plus anti-CTLA-4 therapy alone, a significant proportion of tumors continued to grow (40%)." (PMID 29377881, 2018). "a-CTLA4-TGFβRII was far more effective than a-CTLA-4 in counteracting Treg-mediated suppression and restoring activation of tumor antigen-specific T cells in the presence of autologous Tregs." (PMID 29467463, 2018).